PRKD3 (protein kinase D3)
Description:
Converts transient diacylglycerol (DAG) signals into prolonged physiological effects, downstream of PKC. Involved in resistance to oxidative stress (By similarity).
Synonyms: EPK2; PRKCN; PKD3; PKC-NU; nPKC-NU
Tractability: Small molecule: an approved drug acts on it; a high-quality ligand is known; it belongs to a druggable protein family. Antibody: its Gene Ontology location is reachable by antibodies, with high confidence; the Human Protein Atlas places it where antibodies can reach. PROTAC: ubiquitination databases record sites on it; a small molecule that binds it is known.
Target class: Kinase; Protein Kinase; Enzyme; CAMK protein kinase group; CAMK protein kinase PKD family
Gene: Protein-coding gene on chromosome 2 (37,250,502 to 37,324,833, reverse strand). Ensembl gene ENSG00000115825.
Subcellular location: Cytoplasm; Membrane
Subcellular location (Human Protein Atlas): Cytosol; Plasma membrane; Basal body; Nucleoplasm; Vesicles
Pathways (Reactome):
Metabolism: Sphingolipid de novo biosynthesis
Gene Ontology:
Molecular function: kinase activity; protein binding; diacylglycerol-dependent serine/threonine kinase activity; diacylglycerol-dependent, calcium-independent serine/threonine kinase activity; protein serine/threonine kinase activity; ATP binding; protein kinase activity; protein serine kinase activity
Biological process: intracellular signal transduction; phospholipase C-activating G protein-coupled receptor signaling pathway; protein phosphorylation; sphingolipid biosynthetic process
Cellular component: cytosol; plasma membrane; cytoplasm; membrane
Genetic constraint (gnomAD): Loss-of-function variants: 40 observed, 76.38 expected, observed/expected ratio (o/e) 0.52, 90% interval 0.41 to 0.68. The upper end of that interval is the gene's LOEUF score, 0.68, which puts it in group 2 of 6, group 1 being the genes least tolerant of losing a copy. Missense variants: 911 observed, 991.9 expected, observed/expected ratio (o/e) 0.92, 90% interval 0.87 to 0.97. Synonymous variants: 352 observed, 327.47 expected, observed/expected ratio (o/e) 1.07, 90% interval 0.98 to 1.17.
Homologues: Orthologues: chimpanzee PRKD3 (100% identical), macaque PRKD3 (99% identical), pig PRKD3 (98% identical), rabbit PRKD3 (97% identical), dog PRKD3 (97% identical), guinea pig PRKD3 (97% identical), mouse Prkd3 (96% identical), rat Prkd3 (96% identical), zebrafish prkd3 (82% identical), Caenorhabditis elegans dkf-2 (51% identical), Drosophila melanogaster PKD (51% identical), Caenorhabditis elegans dkf-1 (35% identical). Paralogues in human: PRKD1 (70% identical), PRKD2 (64% identical).
Diseases named in the same sentence as PRKD3 in open-access papers:
PRKD3 is named in the same sentence as 33 diseases in open-access papers, as found by Europe PMC text mining. Sharing a sentence is not in itself a finding about the gene and the disease. The quoted sentences say what the papers report.
breast cancer (11 papers, 2018 to 2025). A primary or metastatic malignant neoplasm involving the breast. "Some protein kinases were involved in the pathogenesis and progression of breast cancer, and PRKD3 was linked to prostate cancer, however, very rare mutations of PRKD3 was observed in ovarian cancer." (PMID 36338962, 2022). "MiR-301b promoted cell proliferation by regulating PRKD3 in ER-mutant breast cancer, accounting for up to 30% of metastatic ER-positive breast cancer." (PMID 37508580, 2023). "Knockdown of PRKD3 decreased the migration of ER- breast cancer cells with increased cell spreading and altered F-actin organization." (PMID 33403031, 2021). "Deletion of PRKD3 by CRISPR/Cas9 in breast cancer cell lines suppressed phosphorylation of ERK1 and c-MYC and led to reduced cell proliferation in vitro and tumor growth in vivo." (PMID 33807058, 2021). "PRKD3 promotes cancer cell proliferation, growth, migration, and invasion in various tumor types including colorectal, gastric, hepatic, prostate, and breast cancer." (PMID 33403031, 2021). "Remarkably, we confirmed the selected strengthened looping genes and differential expressed genes within Hippo relevant pathways in 3D spheroids and further validated PRKD3 in organoids of breast cancer tissues by 3D-FISH." (PMID 34535185, 2021). "The results of the cell proliferation assay showed that knocking out PRKD3 in the breast cancer cells led to the inhibition of cell proliferation." (PMID 31944568, 2020). "We found that the mRNA levels of VEGF, MTA1, PEG10 and hTERT in the PRKD3‐knockout breast cancer cells were lower than the ones in the parental cells." (PMID 31944568, 2020). "Since the luciferase activity of the lysate extracted from the PRKD3‐sgRNA‐1‐edited cells was higher than the one from the PRKD3‐sgRNA‐2‐edited cells, we decided to use PRKD3‐sgRNA‐1 to knockout PRKD3 gene in the two breast cancer cell lines." (PMID 31944568, 2020). "We also found that knocking out PRKD3 in the breast cancer cells led to the down‐regulation of the c‐MYC target genes such as VEGF, MTA1, PEG10 and hTERT and c‐MYC‐related genes such as CCND, CCNE and E2F." (PMID 31944568, 2020). "In order to confirm that PRKD3 activated ERK1/c‐MYC axis in the breast cancer cells, we analysed the amounts of the phosphorylated and total ERK1/2 or c‐MYC by performing Western blotting." (PMID 31944568, 2020). "Collectively, our data strongly suggested that PRKD3 likely promote the cell proliferation in the breast cancer cells by activating ERK1‐c‐MYC axis." (PMID 31944568, 2020). "Our study provided the evidence to support that the PRKD3/ERK1/c‐MYC pathway play an important role in breast cancer progression." (PMID 31944568, 2020). "Together, these results show that PRKD1, PRKD2 and PRKD3 are expressed in breast cancer and that PRKD1 mRNA expression is an independent prognostic factor in the entire BC population and in the TNBC subpopulation." (PMID 29796183, 2018). "Besides functioning in proliferation of breast cancer cells, PRKD3 also promotes the motility, spreading, and migration of breast cancer." (PMID 33403031, 2021). "Besides breast cancer, increased levels of PRKD3 were detected in human prostate cancer specimens when compared to normal prostate specimens." (PMID 33403031, 2021). "PRKD3 appears to have typical oncogenic effects in breast cancer." (PMID 33403031, 2021). "Additionally, ectopic expression of PRKD3 in the PRKD3‐knockout breast cancer cell lines led to the increased amount of p‐ERK1(Thr202/Tyr204), p‐c‐MYC, and c‐MYC." (PMID 31944568, 2020). "Previous study suggested that Protein Kinase D3 (PRKD3) was involved in breast cancer progression." (PMID 31944568, 2020). "In addition, Immunofluorescence staining showed that p‐ERK1/2 (Thr202/Tyr204), p‐c‐MYC (Ser62) and c‐MYC were down‐regulated by knocking out PRKD3 in breast cancer cells." (PMID 31944568, 2020).
breast cancer (continued). "In addition, the proliferation of the breast cancer cells and the tumour growth in xenograft mouse models were promoted by both the PRKD3 overexpression and the ERK1/c‐MYC axis activation." (PMID 31944568, 2020). "To determine whether the expression of PKD family members is associated with prognosis in breast cancer, we first analyzed PRKD1, PRKD2 and PRKD3 mRNA levels by quantitative RT-PCR in a large series of 527 primary breast tumors with known clinical/pathological status and long-term outcome." (PMID 29796183, 2018). "In short, we suggested that PRKD3 functions as an upstream regulator of ERK1/c‐MYC axis and promotes the proliferation of the breast cancer cells." (PMID 31944568, 2020). "Our current data showed that knocking out PRKD3 led to the reduction of p‐ERK1, p‐c‐MYC (Ser62), total c‐MYC and the down‐regulated expression of c‐MYC target genes in breast cancer cells." (PMID 31944568, 2020). "Although previous studies have demonstrated that PRKD3 is an oncogenic function in invasive breast cancer, and MET has a potential prognostic value in breast cancer, our study further elicits their potential prognostic values in predicting the outcome of endocrine therapy." (PMID 34535185, 2021). "The positive correlation of the transcript levels among PRKD3, ERK1 and c‐MYC in the human breast cancer tissues was not significant, supporting that PRKD3 activated ERK1/c‐MYC axis independent of up‐regulating the transcript levels of the ERK1 and c‐MYC." (PMID 31944568, 2020). "In short, our study indicated that PRKD3 likely promoted the proliferation of breast cancer cells by activating ERK1/c‐MYC axis, but not ERK2‐mediated pathways." (PMID 31944568, 2020). "However, the amounts of p‐ERK2 (Thr202/Tyr204) and ERK1/2 in the breast cancer cells were not reduced in the PRKD3‐knockout cells." (PMID 31944568, 2020). "More specifically, the aberrant expression of PRKD3 has been identified in cancer cells of various tumor types, including colorectal cancer (CRC), gastric cancer (GC), liver cancer (LC), prostate cancer (PC) and breast cancer (BC)." (PMID 39859313, 2025). "However, the oncogenic mechanisms of PRKD3 in breast cancer is not fully investigated." (PMID 31944568, 2020). "Taken together, our studies suggested that PRKD3 regulated phosphorylation of ERK1, not ERK2, and then ERK1 stabilized c‐MYC by phosphorylation, leading to promote the proliferation of the breast cancer cells." (PMID 31944568, 2020). "Our previous studies have suggested that PRKD3 was overexpressed in triple‐negative breast cancer cell lines (MDA‐MB‐468, MDA‐MB‐231).2, 12 In order to study PRKD3 signalling pathway in breast cancer, CRISPR/Cas9 technology was applied for knocking out PRKD3 in the cells." (PMID 31944568, 2020).
prostate carcinoma (6 papers, 2015 to 2022). A carcinoma that arises from epithelial cells of the prostate gland. "Other studies had confirmed that PRKD3 was highly expressed in prostate cancer and played a role in regulating tumor cell migration and invasion." (PMID 35281088, 2022). "PRKD3 promotes the growth and survival of prostate cancer cells through AKT serine/threonine kinase 1 and mitogen-activated protein kinase 1 signaling pathway." (PMID 33403031, 2021). "Interplay of PRKD3 with sterol regulatory element binding transcription factor 2 also contributes to the growth of prostate cancer cells via upregulating lipogenesis." (PMID 33403031, 2021). "Then, lncRNA PCA3 inhibits the translation of PRKD3 (serine/threonine-protein kinase D3) protein via competitive miR-1261 sponging and in that way promotes the invasion of prostate cancer cells." (PMID 31947678, 2020). "Inducible silencing of PRKD3 inhibits secretion of tumor-promoting factors (matrix metallopeptidase 9, Interleukin 6, C-X-C motif chemokine ligand 8, and C-X-C motif chemokine ligand 1) in prostate cancer." (PMID 33403031, 2021). "Snail activated the lncRNA PCA3 expression could inhibit PRKD3 protein translation via competitive miR-1261 sponging to promote the invasion and migration of prostate cancer." (PMID 33403031, 2021). "Chen suggested that PRKD3 could promote prostate cell proliferation by activating downstream AKT and ERK1/2 molecules, and the absence of PRKD3 could lead to the arrest of cell cycle G0/G1 phase of prostate cancer cell line." (PMID 35281088, 2022).
triple-negative breast carcinoma (6 papers, 2021 to 2025). An invasive breast carcinoma which is negative for expression of estrogen receptor (ER), progesterone receptor (PR), and human epidermal growth factor receptor 2 (HER2). "Protein kinase D3 (PKD3) is an important regulator of triple-negative breast cancer (TNBC) progression by promoting invasion, proliferation, and stem cell maintenance." (PMID 40970203, 2025). "Huck pointed out that PRKD3 promoted growth of triple negative breast cancer cells by activating mTORC1-S6K1 pathway." (PMID 35281088, 2022). "This study defines protein kinase D3 (PRKD3) to be the key regulator of clusterin (CLU) in promoting triple negative breast cancer (TNBC) tumor growth." (PMID 33643800, 2021). "In addition, PRKD3 promotes triple-negative breast cancer tumor growth by inhibiting the lysosomal distribution and degradation of CLU37." (PMID 36131026, 2022). "Furthermore, PRKD2 and PRKD3 are preferentially expressed in triple-negative breast cancer (TNBC)." (PMID 34249722, 2021).
gastric cancer (4 papers, 2022 to 2026). A primary or metastatic malignant neoplasm involving the stomach. "Sex-specific GWAS in males identified a significant association in PRKD3, which PheWAS linked to neoplasms and stomach cancer." (PMID 40021682, 2025). "Our results revealed that PRKD3 expression was highly heterogeneous, showing significant upregulation in liver cancer, gastric cancer, and adrenocortical carcinoma, and downregulation in others." (PMID 41931575, 2026).
melanoma (3 papers, 2012 to 2021). A malignant, usually aggressive tumor composed of atypical, neoplastic melanocytes. "PRKD3 acts as an important role as well as diagnostic criteria in gastric, melanoma, and hepatocellular cancer." (PMID 33403031, 2021). "In melanoma cells, PRKD3 sensitizes RAF inhibitor RAF265 by preventing reactivation of mitogen-activated protein kinase 1 signaling." (PMID 33403031, 2021). "In a study of Raf265-resistant melanomas containing the BRAF V600E mutation, it was observed that protein kinase D3 (PRKD3) mediated resistance to both Raf and MEK inhibitors and siRNA knockdown of PRKD3 cooperated with Raf265 in suppressing the growth of the resistant melanoma cells." (PMID 23085539, 2012).
ovarian carcinoma (3 papers, 2015 to 2023). A malignant neoplasm originating from the surface ovarian epithelium. "Since PRKD3 very rarely mutates in ovarian cancer, it is difficult to detect by the individual methods." (PMID 25961669, 2015).
breast tumors (2 papers, 2018 to 2020). "In this study, we reported that PRKD3 activated ERK1‐c‐MYC axis to promote the breast tumour growth." (PMID 31944568, 2020).
invasive breast carcinoma (2 papers, 2020 to 2021). A carcinoma that infiltrates the breast parenchyma. "In addition, PRKD3 has been previously reported to have an important role in promoting the growth and progression of invasive breast cancer." (PMID 32641122, 2020).
Alzheimer disease (1 paper, 2021). A progressive, neurodegenerative disease characterized by loss of function and death of nerve cells in several areas of the brain leading to loss of cognitive function such as memory and language. "Here, we add six variants associated with Alzheimer’s disease risk (near APP, CHRNE, PRKD3/NDUFAF7, PLCG2 and two exonic variants in the SHARPIN gene)." (PMID 34099642, 2021).
brain glioma (1 paper, 2012). A malignant glioma that involves the brain. "Only sporadic mutations have been described in the PRKD3 gene in lung adenocarcinoma, ovary and brain glioma (COSMIC and ICGC databases)." (PMID 22675518, 2012).
colorectal cancer (1 paper, 2026). A primary or metastatic malignant neoplasm that affects the colon or rectum. "PRKD3 mRNA levels were quantified by quantitative real-time polymerase chain reaction (qPCR), and its protein expression in colorectal cancer cell lines was detected by Western blot analysis." (PMID 41980898, 2026).
dementia (1 paper, 2021). Loss of intellectual abilities interfering with an individual's social and occupational functions. "The SNPs rs876461 (PRKD3; P = .02), rs117618017 (APH1B; P = .03), rs4844610 (CR1; P = .04), rs7584040 (BIN1; P = 2 × 10–3), rs11168036 (HBEGF; P = 8 × 10–3), rs143429938 (CLU/MIR6843; P = .04), and rs8064326 (KCTD2; P = 3 × 10‐4) were independently associated with incident dementia." (PMID 33532541, 2021).
heart failure (1 paper, 2023). Inability of the heart to pump blood at an adequate rate to meet tissue metabolic requirements. "Findings from GWAS and Mendelian randomization-proteomics identify seven (CAMK2D, PRKD1, PRKD3, MAPK3, TNFSF12, APOC3 and NAE1) proteins as potential targets for interventions to be used in primary prevention of heart failure." (PMID 37429843, 2023).
liver fibrosis (1 paper, 2021). "It has also been demonstrated that global Prkd3-knockout and myeloid cell-specific Prkd3-knockout mice developed spontaneous liver fibrosis." (PMID 33807058, 2021).
ovarian tumors (1 paper, 2015). "As an example, PRKD3 only mutates in 3 ovarian tumors, with a mutation rate as low as 0.0095 (3/316 = 0.0095), and all 3 are missense mutations that have mild impact on protein structure." (PMID 25961669, 2015).
rectal cancer (1 paper, 2026). A primary or metastatic malignant neoplasm that affects the rectum. "PRKD3 expression was significantly associated with the clinical diagnosis (colon vs. rectal cancer) (p < 0.05)." (PMID 41980898, 2026).
salivary gland tumours (1 paper, 2024). "The detection of a PRKD1 p.Glu710Asp hotspot mutation or the translocation of one of the PRKD1, PRKD2, or PRKD3 genes is now considered highly specific for the diagnosis of PAC, as these molecular alterations are rarely detected in other salivary gland tumours." (PMID 38201647, 2024).
serous ovarian cancer (1 paper, 2022). "On the other hand, the analysis of phosphoproteomic data indicated that the protein abundance of PRKD3 was correlated with poor overall survival of patients with high-grade serous ovarian cancer." (PMID 36338962, 2022).